FMR1 (fragile X messenger ribonucleoprotein 1)
Diseases named in the same sentence as FMR1 in open-access papers (continued):
Sharing a sentence is not in itself a finding about the gene and the disease.
fragile X-associated tremor/ataxia syndrome (continued). "Fragile X-associated tremor/ataxia syndrome is a late-onset neurodegenerative condition that manifests in some carriers of the FMR1 premutation; approximately 40–75% of males and 16–20% of females with a premutation develop FXTAS." (PMID 30717399, 2019). "Fragile X-associated tremor/ataxia syndrome (FXTAS) is a neurodegenerative disorder characterized by a late onset and slow progression caused by a premutation (55-200 CGG repeat) in the fragile X mental retardation (FMR1) gene." (PMID 41840821, 2026). "In recent studies, however, unique disorders related to the premutation in the FMR1 gene have been reported, including the Fragile X-associated primary ovarian insufficiency (FXPOI) and Fragile X-associated tremor/ataxia syndrome (FXTAS), with abnormal gait, memory, and executive dysfunction." (PMID 36983968, 2023). "Fragile X-associated tremor/ataxia syndrome (FXTAS) is an adult-onset neurodegenerative disorder caused by a CGG repeat expansion (55–200 repeats, premutation) within the 5′ UTR of the fragile X gene (fragile X messenger ribonucleoprotein 1 gene, FMR1)." (PMID 38139097, 2023). "Carriers of the fragile X premutation, an allelic variant of the FMR1 gene with 55–200 cytosine-guanine-guanine (CGG) repeats, are at risk of developing a late-onset, progressive neurodegenerative disease—fragile X-associated tremor/ataxia syndrome (FXTAS)." (PMID 35321639, 2022). "Its main pathogenic gene is fragile X mental retardation 1 (FMR1) gene associated with intellectual disability, autism, and fragile X-related primary ovarian insufficiency (FXPOI) and fragile X-associated tremor/ataxia syndrome (FXTAS)." (PMID 31191598, 2019). "The CGG expansion to premutation range (55-200 CGG repeats) is equivalent to the FXS carrier status and may cause FMR1-dependent disorders − fragile X-associated primary ovarian insufficiency (FXPOI) and fragile X-associated tremor/ataxia syndrome (FXTAS)." (PMID 29641417, 2018). "Many have postulated that FMR1 mRNA toxicity may underlie FXPOI, as is the case for the other PM-associated disorder, fragile X-associated tremor/ataxia syndrome (FXTAS)." (PMID 25147555, 2014). "Long non-coding RNAs may participate in the pathogenesis of fragile X syndrome (FXS) and fragile X tremor ataxia syndrome (FXTAS), both of which are caused by the aberrant expansion of CGG trinucleotide, repeat in the 5′ UTR of protein-coding fragile-X mental retardation 1 gene (FMR1)." (PMID 24036441, 2013). "While this approach shows promise, there is also some concern about gene reactivation as there is a premutation in the FMR1 gene, where 55-200 CGG repeats do not induce hypermethylation but cause Fragile X-associated tremor/Ataxia Syndrome (FXTAS)." (PMID 38510848, 2024). "Fragile X-associated tremor/ataxia syndrome (FXTAS, #300623) is a neurodegenerative disorder affecting individuals with a premutation CGG-expansion (55–200 repeats) in the 5′ untranslated region (UTR) on the Fragile X mental retardation 1 (FMR1) gene on the X-chromosome." (PMID 30984240, 2019). "A G4-forming (CGG)n repeat expansion within mutant forms of the FMR1 gene locus induces aberrant expression of the G4 binding protein FMRP which leads to the neurodevelopmental Fragile-X syndrome (FXS), or the repeat-length-dependent neurodegenerative Fragile-X tremor and ataxia syndrome (FXTAS)." (PMID 32870280, 2020). "While carriers of FMR1 premutation alleles do not develop FXS, 40% of male and 16–20% of female premutation carriers suffer from fragile X-associated tremor/ataxia syndrome (FXTAS), and 20% of female carriers are reported to develop fragile X-associated primary ovarian insufficiency (FXPOI)." (PMID 37628570, 2023).
Anxiety (117 papers, 2009 to 2025). Intense feelings of nervousness, tension, or panic often arise in response to interpersonal stresses. "In zebrafish, mutations in the fmr1 result in anxiety-like behaviours, hyperactivity, and heightened sensitivity to auditory and visual stimuli." (PMID 40809946, 2025). "The cell-type-specific loss of Fmr1 in PV-expressing neurons led to anxiety-like behavior, impaired social behavior, and dysregulated de novo protein synthesis." (PMID 41210134, 2025). "Gaboxadol was highly efficacious in rescuing behaviours, typically associated with FXS such as aggression, anxiety, hyperactivity and stereotypy, while ibudilast effectively reversed cognitive deficits in Fmr1 KO mice." (PMID 38226317, 2024). "The largest number of DEGs associated with neurogenesis and making the largest contribution to C_A20 differences are associated with an abnormal anxiety-related response (Nr1d1, Fmr1, Atf2, and Pten)." (PMID 36769363, 2023). "Among the genes coexpressed with Fmr1, genes Spred1 and Pten have already been characterized as genes associated with an abnormal anxiety-related response (Rat Genome Database)." (PMID 36769363, 2023). "Further behavioral phenotyping showed the prevention of anxiety-like behaviors caused by CRS upon Fmr1 gene silence." (PMID 36658152, 2023). "Women with the FMR1 premutation are at elevated risk for neuropsychiatric disorders, including anxiety and depression, and the stress of raising a child with FXS can exacerbate these symptoms." (PMID 36081464, 2022). "For example, our results for the elevated plus maze indicated that loss of Fmr1 resulted in decreased anxiety only in the perinatal paradigm (around the age of PD60)." (PMID 35089938, 2022). "FXS patients and the disease model of FXS, the Fmr1 KO mouse, exhibit multiple symptoms associated with neuronal and circuit hyperexcitability, such as sensory hypersensitivity, social anxiety and seizures." (PMID 32161037, 2020). "Overexpression of TrkB in transgenic mice reduces anxiety and the increased TrkB expression in Fmr1 KO mice was likely linked with the reduced anxiety." (PMID 24904293, 2014). "Increased risks for depression and anxiety have been described as being related to genetic risk associated with an FMR1 expansion, with some reports noting increased risks for carrier women prior to having a child with FXS." (PMID 25250044, 2014). "Mechanistically, such disruptions could stem from direct effects of FMR1 loss on sleep and circadian circuits, or indirectly from secondary symptoms such as anxiety, sensory hypersensitivity, and repetitive behaviors." (PMID 40928213, 2025). "Severe behavioral problems were observed in all cases, including aggression, tantrum, self-harming, anxiety, and defiant behavior, due to different mutations of the FMR1 gene, in addition to biological exposure, home environmental factors, and potentially to additional background gene effects." (PMID 40243429, 2025). "Indeed, genetic deletion of H1 (an activity-inducible isoform of Homer1) restored regular mGluR5-long Homer association in the Fmr1 KO and corrected much of the mGluR5 dysfunction as well as behavioral phenotypes, including anxiety and audiogenic seizures." (PMID 31035599, 2019). "Our data does suggest however that the FMR1 premutation, coupled with potential differences in life stressors, may create unique contributions to depression and anxiety outcomes; further evaluation of underlying mechanisms is necessary to provide more specific therapeutic interventions." (PMID 36816716, 2023). "There is also evidence that Fmr1 KO mice may replicate the heightened anxiety associated with FXS." (PMID 24550778, 2014). "Several studies in Fmr1 KO mice show overactive cholinergic signaling including deficits in learning which can contribute to anxiety, repetitive behavior, and hypersensitivity." (PMID 41469555, 2025).
Anxiety (continued). "In the anxiety test, Fmr1 KO mice spent more time in the open arms of the EPM and were more hyperactive in the open field test regardless of the treatment." (PMID 39604505, 2025). "A hyperactive cholinergic system can contribute to learning, hypersensitivity and anxiety issues reported in Fmr1 KO mice." (PMID 41469555, 2025). "Gaboxadol, a δ-subunit-selective, extrasynaptic GABAA receptor agonist that rescues FXS-related behaviors in Fmr1 KO mice, such as aggression, anxiety, hyperactivity, and stereotypies." (PMID 41210134, 2025). "Monotherapy gaboxadol treatment (0.5 or 1.5 mg/kg) significantly reduced anxiety, as measured by hyponeophagia, in Fmr1 KO mice to levels observed in WT mice." (PMID 38226317, 2024). "On the contrary, however, Fmr1 KO mice after fluoxetine treatment have reduced anxiety but enhanced explorative activity during the open field test, with abnormal changes of BDNF/TrkB signaling in the hippocampus." (PMID 38716113, 2024). "We did demonstrate that gaboxadol effectively normalized behaviours such as hyperactivity, aggression, stereotypy and anxiety in Fmr1 KO mice." (PMID 38226317, 2024). "The percentage of time spent in the open arms was increased in Fmr1-KO in comparison to the WT-control mice, under vehicle and 10 mg/kg/day Apocynin treatment, reflecting a reduced anxiety response in the Fragile X mouse model." (PMID 39767793, 2024). "Our study revealed that the superimposition of a high seizure load on Fmr1 KO mice resulted in an increased latency to the first nose poke and decreased anxiety-like behavior." (PMID 39335388, 2024). "Decreased anxiety-like behavior in the open field as described in multiple Fmr1 KO models is consistent with our findings." (PMID 39335388, 2024). "Our study revealed that the superimposition of a high seizure load on Fmr1 KO mice resulted in an increased latency to the first nose poke and deceased anxiety-like behavior." (PMID 39335388, 2024). "Deletion of the FMR1 gene in these mice resulted in more repetitive and less anxiety-like behavior compared to WT mice." (PMID 39335388, 2024). "In the current study, we found that the superimposition of a high seizure load on Fmr1 KO mice resulted in decreased anxiety-like behavior." (PMID 39335388, 2024). "Current experiment results from the open field test and elevated plus maze indicate that Fmr1-KO mice exhibit high anxiety levels, and mice of the fragile X premutation (CGG repeat sequences between 55 and 200) demonstrate an indication of “social anxiety”." (PMID 38716113, 2024). "Further studies would be necessary to discriminate between approach-avoidance and anxiety-like behaviors in the Fmr1 KO mice." (PMID 39308631, 2024). "From our current report, we can further conclude that LP-211 rescues some of the behavioral abnormalities including repetitive behaviors in Fmr1-KO mice and it seems that LP-211 can also be used to ameliorate anxiety." (PMID 37065917, 2023). "Acute LP-211 administration did not affect the behavioral abnormalities observed in BTBR mice but improved repetitive behavior in Fmr1-KO mice and showed a trend to change anxiety of this strain." (PMID 37065917, 2023). "The weight difference was lost for 10 days after weaning, from p21-p30, likely due to increased anxiety of Fmr1 KO mice after separation from their mothers, that has been demonstrated." (PMID 37542065, 2023). "Fmr1 knockout mice exhibit a decreased corticosterone response to an acute stressor and reduced anxiety in open-field and elevated plus maze tests." (PMID 36769363, 2023). "Both GRM5R/R and Fmr1 KO mice with disrupted scaffolding exhibit low levels of anxiety-like behavior in the elevated plus maze, posing intact mGlu5-Homer2 scaffolds as drivers of negative affect in this paradigm." (PMID 36973011, 2023). "Fmr1-knock out (KO) mice present hyperactivity, repetitive behavior, seizure, and social impairments as well as altered anxiety, thus recapitulating FXS symptoms of humans." (PMID 37065917, 2023).
Anxiety (continued). "Increased anxiety has also been reported in the mirrored chamber test, in which Fmr1 KO mice show a greater aversion to the central mirrored chamber." (PMID 36692473, 2023). "Remarkably, increased PV levels and enhanced PNN formation in the auditory cortex of Fmr1 KO mice following MMP-9 inhibition is correlated with decreased anxiety and hyperactivity during adolescence (PND 27–28)." (PMID 37188005, 2023). "Our data therefore further underline the inconsistency of the emotional phenotype of Fmr1-KO mice, in contrast with what is typically observed in FXS patients who exhibit a robust increase in anxiety levels." (PMID 37566006, 2023). "Next, we performed a battery of tests to assess motor function, anxiety, repetitive, stereotypic, and social behaviors in Fmr1+/+:Pv-Cre (WT-PV) and Fmr1−/y-PV mice." (PMID 35768828, 2022). "In this study, Fmr1 KO mice revealed low anxiety, and probably high impulsivity in elevated plus maze tasks, which were rescued by pirenperone." (PMID 36470953, 2022). "Cell type-specific deletion of Fmr1 in parvalbumin-expressing neurons resulted in anxiety-like behavior, impaired social behavior, and dysregulated de novo protein synthesis." (PMID 35768828, 2022). "In this study, we treated Fmr1 KO mice subacutely with three different classes of hypnotics and recorded effects on sleep duration, open-field activity, anxiety-like behavior, and social behavior." (PMID 35720683, 2022). "Previous studies have interpreted the reduced anxiety levels displayed by Fmr1-KO mice as a consequence of their altered neurogenesis in the ventral hippocampus and/or reduced corticosterone response to acute stressors." (PMID 36385949, 2022). "This behavioral phenotype was replicated at 18 months of age, but it was accompanied by reduced levels of anxiety that were displayed by Fmr1-KO old mutants only." (PMID 36385949, 2022). "For the caffeine analysis, the main effect of genotype was statistically significant (p < 0.001), also showing that Fmr1 KO mice have decreased anxiety-like behavior compared to WT mice." (PMID 35720683, 2022). "Fmr1 KO mice also display hyperactivity in the open field, decreased anxiety-like behaviors, repetitive behaviors, and learning and memory impairments." (PMID 35833085, 2022). "We chronically sleep-restricted male Fmr1 KO mice and determined the effect on open field activity, anxiety-like behavior, repetitive behavior, sleep duration, and social behavior." (PMID 35833085, 2022). "An exploratory phase 2 open-label clinical trial (ZYN2-CL-009) found that 12-week treatment with ZYN002 resulted in clinically meaningful reductions in anxiety and behavioral symptoms in 20 children and adolescents with FXS and full FMR1 mutation." (PMID 36434514, 2022). "Minocycline reduced audiogenic seizures, hyperactivity and anxiety-like behaviors in both young and adult Fmr1 KO mice, but the effects lasted longer when the treatment was given at a young age." (PMID 34690832, 2021). "In our study, we found that JZL-184 treatment significantly reduced anxiety-like behavior and hyperactivity in Fmr1 KO mice." (PMID 34645383, 2021). "In other Fmr1 KO mouse studies, OV101 also normalized hyperactivity and repetitive, social, and anxiety-like behavior, which have been associated with decreased expression of the GABAA receptor δ subunit and deficient GABAergic tonic inhibition." (PMID 34690787, 2021). "Early treatment of the fmr1 knock-down embryos with mavoglurant, an mGluR5 antagonist, reduced anxiety, increased cognition and reduced circling at 7dpf." (PMID 33671313, 2021). "Overall, these results indicate that JZL-184 treatment reduced anxiety-like behaviors and hyperactivity in Fmr1 KO-treated mice 4 h post-treatment." (PMID 34645383, 2021). "In an initial study, BMS treatment rescued social, cognitive, and anxiety phenotypes and normalized dendritic morphology in the Fmr1-KO mouse." (PMID 34440392, 2021).
Anxiety (continued). "Behavioral assessment of anxiety-like behavior and hyperactivity also showed improvements in these measures in Fmr1 KO mice." (PMID 34645383, 2021). "In our results, we only observed a significant genotype effect for defecation, but we did see significant improvements in hyperactivity and anxiety-like measures in Fmr1 KO mice compared to vehicle-treated Fmr1 KO controls." (PMID 34645383, 2021). "Light/dark test revealed elevated anxiety levels in fmr1 mutants, which spent a higher percentage of time in the light zone at 14dpf and had a reduced number of midline crossings than wild-type." (PMID 33671313, 2021). "In the elevated plus maze test, there were no group differences in the behavioral measurements (p > 0.05), indicating a minimal effect of DA on the anxiety level of Fmr1-KO mice." (PMID 32778145, 2020). "Gene therapy using human FRM1 alleviates the low pre-pulse inhibition, hyperactivity, and anxiety behaviors in Fmr1-KO mice." (PMID 33519379, 2020). "ASD mice models with FMR1, PTEN, UBE3A, and GABRB3 mutations exhibit learning deficits, stereotypic behaviors, and anxiety phenotypes." (PMID 33519379, 2020). "As reported by many research groups, Fmr1 KO mice exhibited impaired memory and exploratory and anxiety-like behaviors, which were ameliorated to some degree by lowering ICAM5 expression in DG, a pivotal area connecting amygdala and prefrontal cortex." (PMID 31882402, 2020). "A decreased MMP-9 activity in the hippocampus of the Fmr1 KO mouse, dendritic spine maturation, improvement in anxiety, and strategic exploratory behavior were observed after treatment with the antibiotic minocycline." (PMID 31035599, 2019). "Specifically, here we investigated the effects of various doses of gaboxadol on hyperactivity, anxiety, aggression, and repetitive behaviors in the Fmr1 KO2 model of FXS, demonstrating the efficacy potential of gaboxadol for treating those FXS symptoms." (PMID 31293404, 2019). "Acamprosate, which activates GABAB and GABAA receptors, also improved several phenotypes like cortical upstate duration, behavioral improvement, anxiety, locomotor tests in Fmr1 KO mouse and reduced ERK1/2 activation in brain tissue." (PMID 31035599, 2019). "Previously published results suggested that anxiety-like behavior was the same between the Fmr1 KO and Fmr1 KO/Fxr2 KO mice based on the open field test and the light:dark box." (PMID 30654445, 2019). "A recent study reported that this STEP inhibitor reduces seizure incidence and hyperactivity, anxiety and improves sociability, electrophysiological deficits in acute brain slices and spine morphology in Fmr1 KO mouse." (PMID 31035599, 2019). "In general, both Fmr1 KO and Fmr1 KO/Fxr2 Het mice traveled more relative distance in the center compared to WT indicating lower anxiety." (PMID 30654445, 2019). "Fmr1 KO mice show reduced anxiety indicated by reduced thygmotaxis in the OFT and in the light-dark exploration test, as well as reduced startle reactivity at high decibel levels (120 dB) of white noise." (PMID 29944857, 2018). "Our data is in line with the fact that the gene was shown to cause abnormal behavior when overexpressed in mice, a specific high-anxiety phenotype that is different from FMR1 knock-out mice." (PMID 30567555, 2018). "Recent experimental evidence has also shown that female Fmr1 KOs present normal fear learning and anxiety, but show impaired fear memory (Nguy & Tejada‐Simon, 2016)." (PMID 29075560, 2017). "There is some evidence of a differential phenotype among the sexes, as male Fmr1 KOs exhibit a reduced anxiety phenotype, whereas females KOs show normal levels of anxiety (Qin, Kang, & Smith, 2005)." (PMID 29075560, 2017).